SETD9 (SET domain containing 9)
Synonyms: C5orf35; MGC33648
Tractability: No criterion of Open Targets' tractability assessment is met for any kind of drug.
Gene: Protein-coding gene on chromosome 5 (56,909,260 to 56,925,532, forward strand). Ensembl gene ENSG00000155542.
Subcellular location (Human Protein Atlas): Nucleoplasm
Gene Ontology:
Molecular function: protein binding; lysine N-methyltransferase activity
Cellular component: mitochondrion; nucleoplasm
Genetic constraint (gnomAD): Loss-of-function variants: 27 observed, 25.59 expected, observed/expected ratio (o/e) 1.06, 90% interval 0.78 to 1.46. The upper end of that interval is the gene's LOEUF score, 1.46, which puts it in group 6 of 6, group 1 being the genes least tolerant of losing a copy. Missense variants: 258 observed, 290.53 expected, observed/expected ratio (o/e) 0.89, 90% interval 0.8 to 0.98. Synonymous variants: 100 observed, 107.36 expected, observed/expected ratio (o/e) 0.93, 90% interval 0.79 to 1.1.
Homologues: Orthologues: chimpanzee SETD9 (99% identical), macaque SETD9 (99% identical), dog SETD9 (93% identical), guinea pig SETD9 (92% identical), pig SETD9 (91% identical), rabbit SETD9 (79% identical), tropical clawed frog setd9 (63% identical), zebrafish setd9 (35% identical).
Diseases named in the same sentence as SETD9 in open-access papers:
SETD9 is named in the same sentence as 4 diseases in open-access papers, as found by Europe PMC text mining. Sharing a sentence is not in itself a finding about the gene and the disease. The quoted sentences say what the papers report.
breast carcinoma (2 papers, 2018 to 2023). "Five of these were strong cross-tissue eQTLs in GTEx (for ATG10, ATP6AP1L, and RPS23, all associated with rs7707921, and C5orf35 (also known as SETD9) and rs889312; P < 1 × 10− 5 in at least 19 tissues with concordant directionality) and maintain their regulatory capacity in breast cancer cells." (PMID 30205839, 2018). "Six of these genes (MRPS30, SETD9, ADGRV1, ZNF703, PRR33, and PSG4) showed different directions of association with breast cancer in epithelial vs. stromal (nonepithelial) cells." (PMID 36690614, 2023).
coronary artery disease (1 paper, 2025). "Previous evidence has linked SETD9 with both coronary artery disease (GCST005196) and blood cell distribution (GCST90025988) supporting SETD9’s involvement in cardiovascular disease." (PMID 40678446, 2025).
SETD9 also shares sentences with these, for which no sentence is quoted: cardiovascular disease (1 paper); prostate carcinoma (1).